RBP5 (retinol binding protein 5)
Description:
Intracellular transport of retinol.
Synonyms: CRBP-III; CRBPIII; CRBP3; HRBPiso
Tractability: Small molecule: a structure with a bound ligand is known; it has a high-quality binding pocket.
Gene: Protein-coding gene on chromosome 12 (7,115,736 to 7,128,889, reverse strand). Ensembl gene ENSG00000139194.
Subcellular location: Cytoplasm
Subcellular location (Human Protein Atlas): Golgi apparatus; Vesicles
Gene Ontology:
Molecular function: protein binding; fatty acid binding; retinoid binding; lipid binding
Biological process: fatty acid transport
Cellular component: extracellular exosome; cytosol; nucleus; cytoplasm
Genetic constraint (gnomAD): Loss-of-function variants: 13 observed, 16.41 expected, observed/expected ratio (o/e) 0.79, 90% interval 0.51 to 1.26. The upper end of that interval is the gene's LOEUF score, 1.26, which puts it in group 5 of 6, group 1 being the genes least tolerant of losing a copy. Missense variants: 160 observed, 155.56 expected, observed/expected ratio (o/e) 1.03, 90% interval 0.9 to 1.17. Synonymous variants: 58 observed, 65.3 expected, observed/expected ratio (o/e) 0.89, 90% interval 0.72 to 1.11.
Homologues: Orthologues: chimpanzee RBP5 (99% identical), pig RBP5 (88% identical), rabbit RBP5 (84% identical), guinea pig RBP5 (52% identical), zebrafish rbp5 (52% identical), zebrafish rbp7a (50% identical), Drosophila melanogaster fabp (27% identical), Caenorhabditis elegans lbp-8 (26% identical), Caenorhabditis elegans lbp-7 (24% identical). Paralogues in human: RBP1 (56% identical), RBP2 (50% identical), RBP7 (49% identical), PMP2 (34% identical), FABP3 (33% identical), FABP12 (31% identical), FABP9 (30% identical), FABP4 (29% identical), FABP5 (29% identical), FABP7 (28% identical), CRABP2 (27% identical), CRABP1 (27% identical), and 3 more.
Diseases named in the same sentence as RBP5 in open-access papers:
RBP5 is named in the same sentence as 16 diseases in open-access papers, as found by Europe PMC text mining. Sharing a sentence is not in itself a finding about the gene and the disease. The quoted sentences say what the papers report.
cholangiocarcinoma (2 papers, 2022 to 2024). A carcinoma that arises from the intrahepatic biliary tree (intrahepatic cholangiocarcinoma) or from the junction, or adjacent to the junction, of the right and left hepatic ducts (hilar cholangiocarcinoma). "RBP5 is involved in many tumor progressions, including hepatocellular carcinoma, cholangiocarcinoma, gastric cancer and lung cancer." (PMID 36054420, 2022).
fibrosis (1 paper, 2018). the formation of excess fibrous connective tissue in an organ or tissue in a reparative or reactive process. "The biological relevance of the other two genes, retinol-binding protein 5 (RBP5) and O6-methylguanine-DNA methyltransferase (MGMT), both of which were hypomethylated in these studies, to the development of NAFLD-related fibrosis remains unknown." (PMID 30005700, 2018).
iron deficiency (1 paper, 2021). "During iron deficiency, association of RBP5 with its mRNA results in increased cytosolic protein concentration which in turn interacts with PAP2 mRNAs downstream." (PMID 34161395, 2021).
keloid (1 paper, 2024). An irregularly shaped, elevated mark on the skin caused by deposits of excessive amounts of collagen during wound healing. "At the same time, PTGFR and RBP5 were down-regulated in keloid." (PMID 39014455, 2024). "Finally, we found that retinoic acid may treat or alleviate keloids by inhibiting RBP5 to differentiate pro-inflammatory fibroblasts (PIF) to mesenchymal fibroblasts (MF), which further reduces collagen secretion." (PMID 39014455, 2024). "In conclusion, the present study provided new immune signatures (PTGFR, RBP5, and LIF) for keloid diagnosis and treatment using multiple bioinformatic analyses and machine learning algorithms." (PMID 39014455, 2024). "LIF was significantly up-regulated in keloids compared to normal skin, while PTGFR and RBP5 were down-regulated in keloids." (PMID 39014455, 2024). "In summary, the present study provides novel immune signatures (PTGFR, RBP5, and LIF) for keloid diagnosis and treatment, and identifies retinoic acid as potential anti-keloid drugs." (PMID 39014455, 2024).
cancer (2 papers, 2024 to 2025). A tumor composed of atypical neoplastic, often pleomorphic cells that invade other tissues. "We found that some tertiary lymphoid structure-related genes such as LAT, RBP5, SKAP1, and CCR6 were positively correlated with MHCsig in pan-cancer." (PMID 38714579, 2024).
RBP5 also shares sentences with these, for which no sentence is quoted: tumor (4 papers); Hepatic steatosis (2); hepatocellular carcinoma (2); age-related macular degeneration (1); dyslipidemia (1); esophageal carcinoma (1); gastric cancer (1); lung carcinoma (1); melanoma (1); Obesity (1); rectum adenocarcinoma (1).